RPIA (ribose 5-phosphate isomerase A)
Diseases named in the same sentence as RPIA in open-access papers:
RPIA is named in the same sentence as 37 diseases in open-access papers, as found by Europe PMC text mining. Sharing a sentence is not in itself a finding about the gene and the disease. The quoted sentences say what the papers report.
colorectal cancer (5 papers, 2016 to 2023). A primary or metastatic malignant neoplasm that affects the colon or rectum. "Ribose-5-phosphate isomerase A (RPIA) regulates tumorigenesis in liver and colorectal cancer." (PMID 35887232, 2022). "Therefore, the upregulation of RPIA in the group of colorectal cancer combined with S. japonicum infection may be related to its poor prognosis." (PMID 37904220, 2023). "In colorectal cancer cells, miR-124 directly targets phosphoribosyl pyrophosphate synthetase 1 (PRPS1) and ribose-5-phosphate isomerase-A (RPIA) and thus inhibits DNA synthesis and proliferation." (PMID 36013278, 2022). "We also identified that the non-canonical function of RPIA activates β-catenin in colorectal cancer and activates ERK and β-catenin pathways in hepatocarcinogenesis." (PMID 35887232, 2022). "Furthermore, it has been shown that microRNAs can target the RPIA gene and the downstream PRPS1 gene that drives nucleoside formation from ribose-5-phosphate, leading to reduced PPP flux and proliferation in human colorectal cancer cells." (PMID 27328773, 2016).
endometritis (4 papers, 2023 to 2025). An acute or chronic, usually bacterial infectious process affecting the endometrium. "Compared to resistant cows, endometritis-affected cows produced considerably more of the genes TLR4, LITAF, TNF-α, TKT, RPIA, TLR7, TNF-α, TKT, and AMPD1." (PMID 39195794, 2024). "Gene expression levels were considerably higher in endometritis-affected cows than in resistant ones for the genes TLR4, TLR7, TNF-α, NCF4, LITAF, OXSR1, TKT, RPIA, and AMPD1." (PMID 37368756, 2023). "The expression levels of the genes TLR4, TLR7, TNF-α, NCF4, LITAF, OXSR1, TKT, RPIA, and AMPD1 were significantly greater in endometritis-affected Holstein dairy cows than in resistant ones." (PMID 37368756, 2023). "The immune (TLR4, TLR7, TNF-α, IL10, NCF4, and LITAF), antioxidant (ATOX1, GST, and OXSR1), and erythritol-related (TKT, RPIA, and AMPD1) genes in endometritis-affected and healthy Holstein dairy cows were characterized in this research using a PCR-DNA sequencing technique." (PMID 37368756, 2023). "Molecular genetic analyses of the immunological (TLR4, TLR7, TNF-α, IL10, NCF4, and LITAF), antioxidant (ATOX1, GST, and OXSR1), and erythritol-related (TKT, RPIA, and AMPD1) genes comparing healthy and endometritis cows found differences in nucleotide sequence and transcript levels." (PMID 37368756, 2023). "Single nucleotide variants (SNPs) in the genes were discovered using PCR-DNA sequencing for immune (TLR4, TLR7, TNF-α, IL10, NCF4, and LITAF), antioxidant (ATOX1, GST, and OXSR1), and erythritol-related (TKT, RPIA, and AMPD1) genes found in resistant and endometritis-infected Holstein dairy cows." (PMID 37368756, 2023). "Nucleotide sequence variations between healthy and endometritis-affected cows were revealed using PCR-DNA sequencing for immune (TLR4, TLR7, TNF-α, IL10, NCF4, and LITAF), antioxidant (ATOX1, GST, and OXSR1), and erythritol-related (TKT, RPIA, and AMPD1) genes were reported by44." (PMID 38459095, 2024). "Nucleotide sequence variations between healthy and endometritis-affected cows were revealed using PCR-DNA sequencing for immune (TLR4, TLR7, TNF-α, IL10, NCF4, and LITAF), antioxidant (ATOX1, GST, and OXSR1), and erythritol-related (TKT, RPIA, and AMPD1) genes." (PMID 37368756, 2023).
hepatocellular carcinoma (4 papers, 2018 to 2022). A malignant tumor that arises from hepatocytes. "Furthermore, the enzyme ribose 5-phosphate isomerase A (RPIA) plays an essential role in carbohydrate metabolism in Enterococcus faecalis and is a prognostic biomarker for human hepatocellular carcinoma." (PMID 34861826, 2021). "RPIA catalyzes the reversible conversion of ribose-5-phosphate to ribulose-5-phosphate and has been shown to play a crucial role in the development of human hepatocellular carcinoma (HCC) through ERK signaling." (PMID 31108873, 2019). "During the anti-aging effect to anti-cancer, we found that human ribose-5-phosphate isomerase A (RPIA) was up-regulated in the tumors of hepatocellular carcinoma (HCC) patients." (PMID 35887232, 2022). "Our previous study showed that in hepatocellular carcinoma (HCC), RPIA regulates tumorigenesis via PP2A and extracellular signal-regulated kinase (ERK) signaling." (PMID 29337987, 2018).
breast carcinoma (2 papers, 2016 to 2018). "However, RPIA may play an inhibitory role in the progression of some tumors, as increased hyper methylation of the RPIA locus has been observed in breast cancer." (PMID 27328773, 2016).
colon cancer (2 papers, 2018 to 2022). "Taken together, we found that RPIA is overexpressed at both the mRNA and protein levels in all stages of colon cancer formation." (PMID 29337987, 2018). "To test the effects of RPIA overexpression on colon cancer formation, we generated transgenic zebrafish that overexpressed RPIA under the control of a gut-specific promoter (ifabp)." (PMID 29337987, 2018). "We found that POU2F1 transcripts were positively correlated with hexokinase 2 (HK2), 6-phosphofructo-2-kinase/fructose-2,6-biphosphatase 2 (PFKFB2), ALDOA, pyruvate kinase M1/2 (PKM), lactate dehydrogenase A (LDHA), G6PD, and ribose 5-phosphate isomerase A (RPIA) levels in the colon cancer tissues." (PMID 34997215, 2022). "Moreover, we found that C-terminal 22 amino acid of RPIA D domain is required for the RPIA-mediated β-catenin activation, stabilization, and enhanced colon cancer cell proliferation." (PMID 29337987, 2018). "Furthermore, RPIA-ΔD was unable to elevate TCF reporter activity in the colon cancer cells." (PMID 29337987, 2018).
liver cancer (2 papers, 2022). An epithelial or non-epithelial malignant neoplasm that arises from the liver. "RPIA overexpression regulates cell proliferation and colony formation ability, and modulates tumor growth in nude mice and the overexpression of RPIA in hepatocyte-induced liver cancer formation in zebrafish." (PMID 35887232, 2022). "Our previous studies indicated that the knockdown of RPIA can reduce cell proliferation and colony formation ability in liver cancer cells by modulating ERK signaling." (PMID 35887232, 2022).
lung carcinoma (2 papers, 2022). "RPIA regulates autophagy by inhibiting LC3 processing; however, whether lung cancer is associated with RPIA mediated autophagy remains vague." (PMID 35887232, 2022). "Consistent with the notion, our results showed that RPIA was up-regulated in the tumor biopsy of lung cancer patients, providing another line of important evidence that PPP plays an important role in the regulation of tumor growth upon dysregulation." (PMID 35887232, 2022). "In conclusion, RPIA knockdown induces ROS levels to activate autophagy, apoptosis, and cellular senescence in lung cancer cells." (PMID 35887232, 2022). "Furthermore, the suppression of RPIA increased the levels of LC3-II and reduced the expression of p62 in both shRPIA#1 and shRPIA#2 cells by Western blot, further supporting that the knockdown of RPIA induces autophagy in A549 lung cancer cells." (PMID 35887232, 2022). "Given that RPIA was up-regulated in the tumor biopsy of lung adenocarcinoma, subsequently, we investigated whether the knockdown of RPIA reduces tumor cell proliferation and inhibits colony formation by using the A549 cell line, which is lung carcinoma epithelial cells." (PMID 35887232, 2022). "Thus, we examined whether the knockdown of RPIA induces p21 expression, and found that RPIA silencing up-regulates p21 mRNA and protein expression levels in A549 lung cancer cells, also in H23 and H358 lung cancer cells." (PMID 35887232, 2022). "Thus, we investigated whether the knockdown of RPIA triggers autophagy in lung cancer cells." (PMID 35887232, 2022). "Interestingly, we found the knockdown of RPIA triggered autophagic vacuoles similar to autophagy cell morphology and decreased the clonogenic formation and cell proliferation rate in A549 lung cancer, suggesting that RPIA could participate in autophagy process and promote tumorigenesis." (PMID 35887232, 2022). "In summary, we demonstrated that the knockdown of RPIA decreased the cell proliferation rate and colony formation ability via the p-ERK pathway and induced ROS to activate apoptosis and autophagy and promote cellular senescence in A549 lung cancer cells." (PMID 35887232, 2022). "Therefore, we examined whether the knockdown of RPIA can also reduce the levels of phosphorylated ERK1/2 (p-ERK1/2) in shRPIA#1 and shRPIA#2 A549 lung cancer cells." (PMID 35887232, 2022).
bipolar disorder (1 paper, 2024). A disorder of the brain that causes unusual shifts in mood, energy, activity levels and the ability to carry out day-to-day tasks. "Lastly, in the pentose phosphate/glutathione pathways, RPIA was upregulated in bipolar disorder but downregulated in ketosis, whereas G6PD was downregulated in both." (PMID 39125835, 2024). "The ketosis gene expression profile was partially discordant with schizophrenia and bipolar disorder and entirely discordant with major depressive disorder, showing significant downregulation of the genes G6PD, GSR, and RPIA." (PMID 39125835, 2024).
brucellosis (1 paper, 2025). Brucellosis is a bacterial infection that spreads from animals to people via unpasteurized dairy products or by exposure to contaminated animal products or infected animals. "Consequently, we harnessed the genetic resistance to brucellosis in goats by modulating the expression of the TKT, RPIA and AMPD genes." (PMID 39825331, 2025).
cataract (1 paper, 2019). Partial or complete opacity of the crystalline lens of one or both eyes that decreases visual acuity and eventually results in blindness. "In CC54, 5 genes (ANAPC1, RPIA, IGF2BP2, CYP2J2 and LRIG1) and 1 disease (Cataract) were extracted as a correlated set." (PMID 31345171, 2019).
graft versus host disease (1 paper, 2021). An immune system disorder that occurs after allogeneic hematopoietic stem cell transplant and is a reaction of donor immune cells against host tissues. "Genes in the high-expression cohorts of FECH, GYPA, RPIA, and XK were highly enriched in ribosome, graft versus host disease, primary immunodeficiency, and B cell receptor signaling pathways, respectively." (PMID 34861826, 2021).
Leukoencephalopathy (1 paper, 2024). This term describes abnormality of the white matter of the cerebrum resulting from damage to the myelin sheaths of nerve cells. "Patients with a deficiency of RPIA presented with leukoencephalopathy and peripheral neuropathy." (PMID 38778156, 2024).
major depressive disorder (1 paper, 2024). An episode of depression lasting two or more weeks without an intervening episode of mania. "Finally, in the pentose phosphate/glutathione pathways, GSR and RPIA were upregulated in major depressive disorder and downregulated in ketosis." (PMID 39125835, 2024).
pancreatic cancer (1 paper, 2019). "Recently, it was proposed that Ribose-5-phosphate isomerase (RPIA), a regulator of LC3 processing and autophagy, contributes to resistance of KRas-dependent pancreatic cancer via the regulation of nucleotide synthesis." (PMID 31878323, 2019).
plague (1 paper, 2020). Plague is a severe bacterial infection caused by the gram-negative bacterium Yersinia pestis. "Our data suggest that high levels of rpiA expression and (presumably) R5P or Ru5P production (i.e. a high metabolic flux through an RpiA-dependent reaction) increase the blockage rate and thus the likelihood of plague transmission." (PMID 32294143, 2020).
ribose 5-phosphate isomerase deficiency (1 paper, 2023). "Homozygous and compound heterozygous pathogenic variants in RPIA cause ribose 5-phosphate isomerase deficiency (RPIAD; OMIM #608611)." (PMID 38137045, 2023).
cancer (14 papers, 2016 to 2025). A tumor composed of atypical neoplastic, often pleomorphic cells that invade other tissues. "Inhibition of RPIA expression can induce ROS levels and activate autophagy, apoptosis and cell senescence in cancer cells, which is a new idea for cancer treatment." (PMID 39711442, 2024). "For instance, we previously showed that inhibition of nucleotide metabolism through suppression of mTORC1 or the pentose phosphate pathway enzyme Ribose 5-Phosphate Isomerase A (RPIA) induces senescence specifically in p16-low cancers." (PMID 33550279, 2021). "Overall, we propose a role for RPIA in the regulation of autophagy, which will have importance for the selection of anti-cancer therapies targeting this novel mode of regulation." (PMID 27328773, 2016). "The pentose phosphate pathway (PPP) is crucial for the survival and proliferation of cancer cells, and ribose-5-phosphate isomerase A (RPIA) is an important component of the PPP, regulating cancer cell growth and tumor development, RPIA was known for its role in oncogenic signaling." (PMID 37904220, 2023). "These in vivo results are consistent with the observation that in cancer cell lines, downregulation of RPIA using microRNA reduces cell growth and colony formation ability, while overexpression of RPIA is correlated with enhanced growth and lower survival rates." (PMID 29337987, 2018). "Several enzymes in the PPP non-oxidative arm, including Ribose 5-Phosphate Isomerase A (RPIA) and Transketolase (TKT) have been found to be involved in cancer." (PMID 38132097, 2023). "Transgenic fish that overexpresses ribose-5-phosphate isomerase A (RPIA) under the control of an intestinal fatty acid-binding protein (ifabp) promoter (Tg(ifabp:RPIA; myl7:EGFP) developed cancer in the gut at ~3 months of age." (PMID 32131390, 2020). "Ribose-5-phosphate isomerase A (RPIA) is an important integral member of the PPP and regulates cancer cell growth and tumorigenesis." (PMID 29337987, 2018). "For instance, while compelling arguments have been made for metabolic products of the PPP in cancer cell regulation, it is possible that RPIA exerts non-enzymatic signaling functions that may contribute to disease." (PMID 27328773, 2016). "However, in colorectal cells, the RPIA enzymatic and catalytic domain deletion mutants still promoted cell proliferation and activated β-catenin downstream target genes, revealing that at least in this type of cancer this is not how RPIA modulates tumor growth." (PMID 29337987, 2018).
tumor (6 papers, 2018 to 2025). "In pancreatic ductal adenocarcinoma (PDAC), RPIA expression is required for maintenance of tumor cells overexpressing KRasG12D, an activated form of Ras." (PMID 29337987, 2018). "In pancreatic and hepatic cancers, RPIA expression is required for maintenance of tumor cells overexpressing KRasG12D, while in HCC, RPIA regulates tumorigenesis via PP2A and ERK signaling." (PMID 29337987, 2018). "Besides, RPIA knockdown slightly suppresses the colony formation of iKras p53L/+ tumor cells in high glucose, the inhibitory effect is significantly enhanced when cells were cultured under low glucose condition." (PMID 37904220, 2023). "In addition, KRAS increases the expression of glycolytic enzymes and the PPP enzyme ribose-5-phosphate isomerase (RPIA) to increase nucleotide synthesis and maintain tumor proliferation." (PMID 35745875, 2022). "RPIA is a key regulator in the non-oxidative branch of the pentose phosphate pathway, and is involved in nucleotide biosynthesis, making RNA and DNA required for uncontrolled tumor growth." (PMID 35887232, 2022).
infection (3 papers, 2016 to 2021). The state of being infected such as from the introduction of a foreign agent such as serum, vaccine, antigenic substance or organism. "Inactivation of three genes of the PPP (tktA, rpe and rpiA) provoked an initial intracellular growth arrest up to 10 h after infection, while at later time points, bacterial multiplication started to resume, especially with the Δrpe and ΔrpiA mutants." (PMID 34339477, 2021). "To investigate the early post-infection role of rpiA in fleas, we used bright-field and fluorescence microscopy techniques to compare the gut contents of insects one day after a meal containing fluorescent WT or ΔrpiA bacteria." (PMID 32294143, 2020). "Our present results (i) highlight the physiopathological and molecular mechanisms leading to flea blockage, (ii) show that the role of a gene like rpiA changes in space and in time during an infection, and (iii) emphasize that evolution is a gradual process punctuated by sudden jumps." (PMID 32294143, 2020). "Lastly, microscopy experiments showed that the rpe mutant was coccoid soon after infection but not later on—suggesting that Rpe is involved in the same functions as RpiA in fleas." (PMID 32294143, 2020).
genetic disorder (1 paper, 2024). "In humans, ribose-5-phosphate isomerase is encoded by the RPIA gene, and its deficiency is a genetic disorder caused by its mutations; RPIA is, in turn, involved in the pentose phosphate pathway (PPP) as part of carbohydrate degradation." (PMID 39061492, 2024).
RPIA also shares sentences with these, for which no sentence is quoted: pancreatic ductal adenocarcinoma (3 papers); Alzheimer disease (1); anemia (1); Azoospermia (1); biotinidase deficiency (1); epilepsy (1); isovaleric acidemia (1); lactic acidosis (1); lung adenocarcinoma (1); malaria (1); myopathy (1); peripheral neuropathy (1); porphyria (1); primary immunodeficiency (1); schizophrenia (1); sideroblastic anaemia (1); transaldolase deficiency (1).